CACNA1H (calcium voltage-gated channel subunit alpha1 H)
Diseases named in the same sentence as CACNA1H in open-access papers (continued):
Sharing a sentence is not in itself a finding about the gene and the disease.
familial hyperaldosteronism (10 papers, 2017 to 2024). "Somatic mutations in four genes (KCNJ5, ATP1A1, ATP2B3 and CACNA1D) have been identified in nearly 60% of the sporadic APAs, while germline mutations in KCNJ5 and CACNA1H have been reported in different subtypes of familial hyperaldosteronism." (PMID 34829937, 2021). "The identification of a novel germline CACNA1H (M1549V) mutation encoding the low voltage activated T-type calcium channel (Cav3.2) has broadened the genomic landscape of familial hyperaldosteronism; the adrenalectomy specimen of one affected individual showed ZG layer hyperplasia." (PMID 29594118, 2018). "Mutation in CACNA1H p.Met1549Val, encoding the pore-forming α1H subunit of the voltage-dependent T-type calcium channel Cav3.2, was found in children with early-onset PA via autosomal dominant transmission, as a cause of familial hyperaldosteronism (FH) type IV." (PMID 35757409, 2022). "Genetic causes of familial hyperaldosteronism have been expanded through the report of germline pathogenic variants in KCNJ5, CACNA1H and CLCN2 genes." (PMID 35813615, 2022). "Recently, germline mutations in the CACNA1H gene, encoding for the alpha subunit of a L-type voltage-gated calcium channel (Cav3.2), were discovered to be responsible for a novel form of familial hyperaldosteronism (type IV) with an incomplete penetrance." (PMID 28420172, 2017). "Rare germline variants of CYP11B2 (encoding aldosterone synthase), CLCN2 (encoding voltage-gated chloride channel ClC-2), KCNJ5, CACNA1H (encoding a subunit of T-type voltage-gated calcium channel CaV3.2), and CACNA1D have been reported in different subtypes of familial hyperaldosteronism." (PMID 31695023, 2019).
primary aldosteronism (10 papers, 2017 to 2025). An endocrine disorder characterized by excessive production of aldosterone by the adrenal glands. "The mutation of CACNA1H increases aldosterone production and is heavily associated with primary aldosteronism." (PMID 34639069, 2021). "The most deleterious variants detected in the CACNA1G and CACNA1H genes, encoding Cav3.1 and Cav3.2, respectively, represent de novo gain-of-function missense mutations causing congenital severe motor and cognitive impairment with cerebellar atrophy and primary aldosteronism, respectively." (PMID 33704440, 2021). "However, somatic mutations in CACNA1H have been scarcely identified in unilateral primary aldosteronism (uPA), because the large gene size of CACNA1H escalates the challenges of sequencing through conventional Sanger’s approach, which could only target selected exons or hotspot regions of the gene." (PMID 35757409, 2022). "Since primary aldosteronism is one of the reported complications of T2D patients with resistant hypertension, we speculate the changes in methylation of CACNA1H in pancreatic cells is the outcome of T2D." (PMID 34639069, 2021).
cardiac hypertrophy (9 papers, 2015 to 2022). "Furthermore, CACNA1H was required for angiotensin II- and pressure overload-induced cardiac hypertrophy in mice through activation of calcineurin/NFAT80,82,83." (PMID 34168192, 2021). "Instead, re-expressed CACNA1H protein might induce cardiac hypertrophy by activating the calcineurin–NFAT pathway." (PMID 34168192, 2021).
Anxiety (7 papers, 2014 to 2025). Intense feelings of nervousness, tension, or panic often arise in response to interpersonal stresses. "Furthermore, the experimental ablation of CACNA1H, a gene already associated with the RR course of MS, was able to trigger affective disorders including anxiety and hippocampus‐dependent recognition memories (Gangarossa, Laffray, Bourinet, & Valjent, 2014)." (PMID 30656857, 2019). "For example, Ntrk3, Tnr, Cacna1h, Clstn2, and Rapgef2 were found to be involved in pathological processes of anxiety." (PMID 33431988, 2021). "Using a wide range of behavioral assays we show that genetic ablation of the cacna1h gene results in an anxiety-like phenotype, whereas novelty-induced locomotor activity is unaffected." (PMID 24672455, 2014). "Our findings reveal that the lack of Cacna1h gene promotes anxiety-related behavior, impairs learning and memory formation and results in a reduced sensitivity to psychostimulants (d-amphetamine and cocaine)." (PMID 24672455, 2014).
absence seizures (6 papers, 2014 to 2025). "Dicer small interfering (Dsi) RNA knockdown of Cacna1h, which encodes Cav3.2, significantly shortened convulsions in the Genetic Absence Epilepsy Rats from Strasbourg (GAERS) model of absence seizures." (PMID 36386164, 2022).
melanoma (6 papers, 2015 to 2023). A malignant, usually aggressive tumor composed of atypical, neoplastic melanocytes. "This was further supported through silencing of CACNA1H transcript in human BRAFi-adaptive melanoma cells." (PMID 32063604, 2020). "To test whether CACNA1H is responsible for the increase in apoptosis and sensitisation in adaptive cells, we silenced CACNA1H gene in human melanoma cells (A375, SK-MEL-28 and HT144) and analysed the effect on cell death and differentiation after treatment with vemurafenib." (PMID 32063604, 2020). "To confirm that knockdown of CACNA1H was responsible for changes in differentiation status, we measured SOX2 expression in human melanoma cells." (PMID 32063604, 2020). "We confirmed that human vemurafenib-adaptive melanoma cells increased expression of T-type calcium channels genes, CACNA1G and CACNA1H compared to parental cells." (PMID 32063604, 2020).
schizophrenia (6 papers, 2017 to 2025). A major psychotic disorder characterized by abnormalities in the perception or expression of reality. "The human CACNA1H gene encodes a T-type calcium channel (Cav3.2), and its mutation is associated with schizophrenia, ASD, and AE, which are all characterized by abnormal memory function." (PMID 30366389, 2018). "The human CACNA1H gene is also associated with schizophrenia, ASD, and absence seizures (AS)." (PMID 30366389, 2018). "Interestingly, none of the reproducible GWAS-associated loci in schizophrenia CACNA1C, CACNA1H, and CACNB2 (Schizophrenia Working Group of the Psychiatric Genomics, 2014) was detected in our dataset." (PMID 28713243, 2017).
amyotrophic lateral sclerosis (5 papers, 2019 to 2025). Amyotrophic lateral sclerosis (ALS) is a neurodegenerative disease characterized by progressive muscular paralysis reflecting degeneration of motor neurons in the primary motor cortex, corticospinal tracts, brainstem and spinal cord. "In addition to ASD, recent studies have reported that loss-of-function CACNA1H variants are implicated in several neurological disorders, including body-wide chronic pain, severe infantile-onset amyotrophy, and amyotrophic lateral sclerosis." (PMID 41067956, 2025).
glioblastoma (5 papers, 2019 to 2022). The most malignant astrocytic tumor (WHO grade IV). "For example, the expression level of the EXT2 gene is increased in glioblastoma; C1QTNF8 promotes temozolomide resistance; CACNA1H promotes GBM cell proliferation and migration." (PMID 34827152, 2021). "Both regions include genes of interest for glioblastoma, such as EXT2, SSTR5, SSTR5-AS1, C1QTNF8 and CACNA1H." (PMID 34827152, 2021).
hyperaldosteronism (5 papers, 2015 to 2026). Overproduction of aldosterone by the adrenal glands, which may lead to hypokalemia and/or hypernatremia. "The heterozygous CACNA1H variants p.(Met1549Ile) and p.(Met1549Val) were associated with early-onset hypertension and hyperaldosteronism." (PMID 40825030, 2025). "Indeed, independently of hyperaldosteronism, CACNA1H variants have already been associated with absence epilepsy and idiopathic generalised epilepsy." (PMID 40540150, 2025). "Despite autosomal dominant inheritance, cases of subjects carrying CACNA1H mutations with no hypertension even in adult age, or without biochemical evidence of hyperaldosteronism, have been described." (PMID 40540150, 2025).
mental disorder (4 papers, 2020 to 2025). A disease that has its basis in the disruption of mental process. "Mutations in genes encoding Cav3 channels (CACNA1G, CACNA1H, and CACNA1I) have been linked to a variety of neurodevelopmental, neurological, and psychiatric diseases designated here as neuronal Cav3 channelopathies." (PMID 32638069, 2020). "Together with genetic associations of CACNA1I (encoding CaV3.3) and to a lesser extent CACNA1H (encoding CaV3.2) with SZ, this suggests that T-Ca2+ channel dysfunction in TRN could represent an early pathological feature of this psychiatric disorder." (PMID 35079122, 2022).
adrenocortical tumors (3 papers, 2021 to 2024). "The findings suggest the involvement of CACNA1H/CaV3.2 in pheochromocytoma development and establish a potential link between the etiology of adrenomedullary and adrenocortical tumor development." (PMID 38864697, 2024). "Of interest, CACNA1H has been reported as a differentially methylated gene distinguishing adrenocortical tumor subgroups." (PMID 38864697, 2024). "The observations propose a possible overlap in the etiology of adrenocortical tumors and provide the rationale for further studies into the role of CACNA1H in the development of PPGL." (PMID 38864697, 2024).
Channelopathies (3 papers, 2019 to 2022). "Taken together, our here described Cacna1h-CRISPRa/i modular approach could thus be used to model transient gain-of-function or loss-of-function effects in the Cacna1h gene and to study CaV3.2 channelopathies in more detail in vivo." (PMID 35069110, 2021). "By using the unique CRISPRa/i toolbox, we demonstrate to specifically modulate Cacna1h gene expression in different cell types in order to closely recapitulate CaV3.2 channelopathies." (PMID 35069110, 2021). "In addition, a transient inhibition of Cacna1h via the Tet-on inducible cacna1h-CRISPRi system in the GAERS rats at different stages during development could also reveal potentially interesting time windows for Cacna1h-associated channelopathies." (PMID 35069110, 2021). "Our Tet-On Cacna1h-CRISPR toolbox system might open new roads for investigating the role of Cacna1h in several channelopathies in more detail." (PMID 35069110, 2021). "Interestingly, the fold-change induction by CRISPRa occurred within a range also observed for CaV3.2 channelopathies, making our Cacna1h-CRISPR system highly suitable for analyzing this particular and also other channelopathies at the functional level." (PMID 35069110, 2021).
developmental delay (3 papers, 2023 to 2025). "We analyzed the allele frequencies of nine single-nucleotide polymorphisms (SNPs) in the CACNA1A, CACNA1C, and CACNA1H genes among pediatric patients with developmental delay/intellectual disability (DD/ID)." (PMID 40725423, 2025).
heart failure (3 papers, 2017 to 2023). Inability of the heart to pump blood at an adequate rate to meet tissue metabolic requirements. "REST also maintains low alpha 1H expression and regulates CACNA1H encoding alpha-subunit of Cav3.2, thereby regulating aldosterone and cortisol production, which are independent predictors of mortality risk for heart failure patients." (PMID 37892159, 2023).
ovarian carcinoma (3 papers, 2020 to 2021). A malignant neoplasm originating from the surface ovarian epithelium. "In a clinical study of solid tumors including gastric, lung and ovarian cancer, expression of T-type calcium channel genes including CACNA1H is used as a prognostic signature for survival." (PMID 34090518, 2021). "Moreover, the Spearman correlation was analyzed to see if L- and T-type calcium channel genes (CACNA1D, CACNA1F, and CACNA1H) were correlated with the expression of stem cell markers in the ovarian cancer patients (GSE53963 and GSE14764)." (PMID 32230901, 2020). "Next, we questioned whether the expression of three L- and T-type calcium channel genes (CACNA1D, CACNA1F, and CACNA1H) correlates with the survival of ovarian cancer patients." (PMID 32230901, 2020). "BKCa and calcium channels may be a suitable pharmacological target for treating recurrence and drug resistance in late-stage ovarian cancer patients who exhibit amplification of the KCNMA1 gene and calcium channel subunits genes (CACNA1D, CACNA1F, and CACNA1H)." (PMID 33923707, 2021).
Primary hyperaldosteronism (3 papers, 2020 to 2024). A form of hyperaldosteronism caused by a defect within the adrenal gland. "In functional studies in HEK293 cells of the recurrent CACNA1H variant M1549V, reported in primary hyperaldosteronism, loss of normal channel inactivation and activation at different potentials were observed." (PMID 38864697, 2024). "Since constitutional CACNA1H variants have previously been associated with primary hyperaldosteronism, CACNA1H was selected for further analysis." (PMID 38864697, 2024). "Constitutional CACNA1H mutations are an underlying cause of familial forms of primary hyperaldosteronism, characterized by hypertension at a young age due to increased calcium influx in adrenocortical cells of the zona glomerulosa." (PMID 38864697, 2024). "Hence, there is reason to predict the functional effects of the CACNA1H variants observed in PCC, especially for those assessed in primary hyperaldosteronism and aldosterone-producing adenoma, respectively." (PMID 38864697, 2024).
Stroke (3 papers, 2013 to 2023). Sudden impairment of blood flow to a part of the brain due to occlusion or rupture of an artery to the brain. "For the extreme contrast of “stroke” versus “long survivor”, only four gene sets – SERPINC1, SLC22A5, CACNA1H, and SLC4A1 [MIM: 109270] – were significant." (PMID 32898326, 2020).
adenoma (2 papers, 2021 to 2024). A neoplasm arising from the epithelium. "However, somatic mutations resulting in the corresponding substitutions I1430T in Cav3.2 (CACNA1H) and I1015S/V in Cav1.3 (CACNA1D) were identified in aldosterone-producing adenomas." (PMID 33704440, 2021).
adrenocortical adenoma (2 papers, 2024 to 2025). "Subsequently, somatic CACNA1H mutations have been found to underlie the development of subsets of sporadic aldosterone-producing adrenocortical adenomas." (PMID 38864697, 2024).
childhood absence epilepsy (2 papers, 2012 to 2018). A familial generalized pediatric epilepsy, characterized by very frequent (multiple per day) absence seizures, usually occurring in children between the ages of 4 and 10 years, with, in most cases, a good prognosis. "For example, CACNA1H gene variants, denoting the α1H pore-forming subunit of T-type calcium channels, were observed in a patient subset diagnosed as having childhood absence epilepsy (CAE)." (PMID 29796346, 2018).
Cognitive impairment (2 papers, 2021 to 2022). Abnormal cognition is characterized by deficits in thinking, reasoning, or remembering. "In ASD, loss-of-function mutations in JARID1C, an X-linked gene encoding H3K4 demethylase, may also be associated with cognitive impairment, as it regulates autism and cognitive dysfunction genes such as SCN2A, CACNA1H, BDNF, and SLC18A1." (PMID 36406755, 2022). "The genes of cognitive impairment modified by histone include GAD1, GAD2, NMDAR, CACNA1H, and BDNF." (PMID 36406755, 2022).
Dystonia (2 papers, 2021 to 2024). An abnormally increased muscular tone that causes fixed abnormal postures. "One candidate gene was selected for follow-up, Calcium Voltage-Gated Channel Subunit Alpha1 H, CACNA1H, due to its links with the known dystonia gene Potassium Channel Tetramerization Domain Containing 17, KCTD17, and with paroxysmal movement disorders." (PMID 33478561, 2021). "Given the established link between CACNA1H and the previously reported dystonia gene KCTD17 and its link with paroxysmal movement disorders, we focused our additional studies on a putative role of CACAN1H in WC." (PMID 33478561, 2021).
Epileptic encephalopathy (2 papers, 2021). A condition in which epileptiform abnormalities are believed to contribute to the progressive disturbance in cerebral function. "Stringer and others recently described a patient with epileptic encephalopathy who harbors a de novo heterozygous in-frame duplication in SCN8A (p.G1625_I1627dup) and an inherited heterozygous missense variant in CACNA1H (p.G318S)." (PMID 34867351, 2021).
glioma (2 papers, 2022 to 2023). A benign or malignant brain and spinal cord tumor that arises from glial cells (astrocytes, oligodendrocytes, ependymal cells). "Here, we explored the role of a calcium channel, voltage-dependent, T-type, alpha 1H subunit (CACNA1H), which encodes T-type Ca2+ channel Cav3.2 in glioma cells." (PMID 37250140, 2023). "Decreased proliferation and increased apoptosis confirmed the inhibitory effect of CACNA1H inactivation on glioma cell growth." (PMID 37250140, 2023). "To explore the specific role of CACNA1H in glioma cells, we inactivated CACNA1H using siRNA technology or CACNA1H inhibitor (ABT-639)." (PMID 37250140, 2023). "Our data highlighted the effect of CACNA1H as an oncogenic gene in human glioma." (PMID 37250140, 2023). "Suppression of CACNA1H activated the ERS and thus induced apoptosis in glioma cells." (PMID 37250140, 2023).
hearing loss (2 papers, 2019 to 2023). "The genes Trpv1, Ngf, and Cacna1h, which have been reported to be closely related to hearing loss, were selected for analysis." (PMID 37049613, 2023). "Accordingly, recent studies have demonstrated the association between Trpv1, Cacna1h, and Ngf genes and the development of sensorineural hearing loss." (PMID 37049613, 2023). "Recent studies have linked the genes Trpv1, Cacna1h, and Ngf with sensorineural hearing loss." (PMID 37049613, 2023). "Additionally, TS was found to regulate several genes related to hearing loss, including Trpv1, Cacna1h, and Ngf, as determined by quantitative real-time polymerase chain reaction (RT-PCR) analysis." (PMID 37049613, 2023).
status epilepticus (2 papers, 2016 to 2020). Status epilepticus is defined as a continuous seizure lasting more than 30 min, or two or more seizures without full recovery of consciousness between any of them. "In a group of genes that were downregulated in CTR animals after kainic acid-induced status epilepticus but not in KO animals, we identified Cacna1h (Cav3.2)." (PMID 25636686, 2016). "The lack of downregulation of Cacna1h mRNA after status epilepticus in SRF KO mice may contribute to their enhanced epileptic phenotype." (PMID 25636686, 2016).
T-cell leukemia (2 papers, 2012 to 2014). A malignant disease of the T-lymphocytes in the bone marrow, thymus, and/or blood. "CACNA1H (calcium channel, voltage-dependent, T type, alpha 1H subunit) encodes a voltage-dependent calcium channel and is located in a region that appears to be hypomethylated in T-cell leukemias." (PMID 22429919, 2012).
adrenal tumors (1 paper, 2022). "We performed a customized and targeted gene panel next-generation sequencing approach on DNA extracted from adrenal tumors for mutations which revealed one novel variant in CACNA1H c.5809G>A (p.Val1937Met)." (PMID 35757409, 2022).
Alzheimer disease (1 paper, 2020). A progressive, neurodegenerative disease characterized by loss of function and death of nerve cells in several areas of the brain leading to loss of cognitive function such as memory and language. "Perhaps a more interesting ontological category is the 11 downregulated genes associated with MAPK signaling pathway, a number of which (Arrb2, Cacna1g, Fgfr4, Taok1, Cacna1h) have been implicated in Alzheimer's disease (AD)." (PMID 33282900, 2020).
antibody deficiency (1 paper, 2023). "Two patients with CACNA1H mutations have been reported to show selective antibody deficiency, whereas patients harboring mutations in the genes encoding ribosomal proteins have been documented to develop common variable immune deficiency." (PMID 36860866, 2023).